RASEF (RAS and EF-hand domain containing)
Description:
[Isoform 1]: Rab GTPase that acts as a dynein adapter protein, thereby activating dynein-mediated transport and dynein-dynactin motility on microtubules. RASEF-mediated dynein motility is Ca(2+)-independent. Also regulates the formation and sorting of zymogen granules and secretion of digestive enzymes by pancreatic acinar cells (By similarity).
Synonyms: RAB45; FLJ31614; TSG
Tractability: Small molecule: a structure with a bound ligand is known. PROTAC: ubiquitination databases record sites on it.
Gene: Protein-coding gene on chromosome 9 (82,979,590 to 83,063,255, reverse strand). Ensembl gene ENSG00000165105.
Subcellular location: Cytoplasm, perinuclear region (Isoform 1); Cytoplasm; Golgi apparatus; Early endosome; Late endosome; Lysosome
Subcellular location (Human Protein Atlas): Microtubules
Gene Ontology:
Molecular function: GDP binding; GTP binding; identical protein binding; G protein activity; GTPase activity; calcium ion binding
Biological process: zymogen granule exocytosis
Cellular component: cytoplasm; cytosol; early endosome; endolysosome; Golgi apparatus; late endosome; lysosome; perinuclear region of cytoplasm
Genetic constraint (gnomAD): Loss-of-function variants: 39 observed, 42.38 expected, observed/expected ratio (o/e) 0.92, 90% interval 0.71 to 1.2. The upper end of that interval is the gene's LOEUF score, 1.2, which puts it in group 5 of 6, group 1 being the genes least tolerant of losing a copy. Missense variants: 628 observed, 594.39 expected, observed/expected ratio (o/e) 1.06, 90% interval 0.99 to 1.13. Synonymous variants: 234 observed, 229.67 expected, observed/expected ratio (o/e) 1.02, 90% interval 0.92 to 1.13.
Homologues: Orthologues: chimpanzee RASEF (99% identical), macaque RASEF (96% identical), dog RASEF (87% identical), rabbit RASEF (86% identical), mouse Rasef (78% identical), rat Rasef (76% identical), tropical clawed frog rasef (66% identical), guinea pig RASEF (66% identical), zebrafish rasef (51% identical). Paralogues in human: RAB44 (23% identical), RAB26 (12% identical), RAB37 (12% identical), RAB12 (11% identical), RAB8B (10% identical), RAB10 (10% identical), RAB15 (10% identical), RAB8A (10% identical), RAB6A (10% identical), RAB17 (10% identical), RAB1A (10% identical), RAB27A (10% identical), and 56 more.
Diseases named in the same sentence as RASEF in open-access papers:
RASEF is named in the same sentence as 15 diseases in open-access papers, as found by Europe PMC text mining. Sharing a sentence is not in itself a finding about the gene and the disease. The quoted sentences say what the papers report.
breast carcinoma (2 papers, 2019 to 2021). "Further, analysis of breast cancer tissue data from the TCGA database showed that RASEF and NCOA2 levels were strongly and positively correlated (R = 0.51, P < 0.0001)." (PMID 30941313, 2019). "Further, to determine whether RASEF downregulation accounted for the anti-proliferative effect of NCOA2 depletion, we assessed breast cancer cell growth after RASEF knockdown in MTS cell proliferation and colony formation assays." (PMID 30941313, 2019). "Subsequent gene expression analyses have shown that human Rab45/RASEF is detected in many cancer cells, such as myeloid leukemia, uveal malignant melanoma, colorectal cancer, lung cancer, and breast cancer." (PMID 34299309, 2021).
chronic myelogenous leukemia (2 papers, 2017 to 2021). "Overexpression of RAB45/RASEF caused apoptosis by activation of caspase-3 and -9 and increased phosphorylation of p38 in chronic myelogenous leukemia cells." (PMID 34299309, 2021).
lung carcinoma (2 papers, 2019 to 2021). "RASEF has been reported to be a novel diagnostic biomarker for lung cancer and play an oncogenic role in lung cancer cell growth, possibly by activating the ERK signaling cascade." (PMID 30941313, 2019). "In human lung cancer cells, endogenous Rab45/RASEF localizes mainly in the cytoplasm; however, the localization mechanism is still unknown." (PMID 34299309, 2021). "Importantly, inhibiting the interaction between Rab45/RASEF-L and ERK1/2 using a cell-permeable peptide that corresponded to the ERK1/2-interacting site of RASEF suppressed the growth of lung cancer cells." (PMID 34299309, 2021). "An immunoprecipitation assay using anti-RASEF antibody revealed the interaction between endogenous RASEF and endogenous ERK1/2 proteins in lung cancer cells." (PMID 34299309, 2021). "RASEF, a member of the Rab GTPase protein family, has been shown to positively regulate ERK signaling cascade in lung cancer." (PMID 30941313, 2019).
acute myeloid leukemia (1 paper, 2021). Acute myeloid leukemia (AML) is a group of neoplasms arising from precursor cells committed to the myeloid cell-line differentiation. "The Rab45/RASEF gene is encoded on the long arm of chromosome 9, where the region is frequently deleted in candidate tumor suppressor genes in patients with acute myeloid leukemia." (PMID 34299309, 2021).
head and neck carcinoma (1 paper, 2024). A carcinoma that arises from the head and neck region. "Among the 60 DETGs, genes such as TFAP2A, CLSPN, RASEF, HIST1H3H, AKT3, and ITPR1 were associated with metastasis to secondary sites, including the lungs, and with head and neck carcinoma." (PMID 39095857, 2024).
melanoma (1 paper, 2019). A malignant, usually aggressive tumor composed of atypical, neoplastic melanocytes. "Of note, RASEF silencing in melanoma resulted from its promotor hypermethylation, and was associated with the prognosis of melanoma patients." (PMID 30845941, 2019).
pulmonary arterial hypertension (1 paper, 2023). Pulmonary arterial hypertension (PAH) is a group of diseases characterized by mean pulmonary artery pressure >20 mmHg and elevated pulmonary arterial resistance leading to right heart failure. "Besides, scientists have found that there is a connection between pulmonary arterial hypertension (PAH) in rat model and hyper methylation of RASEF." (PMID 37900914, 2023).
Right ventricular hypertrophy (1 paper, 2023). In this case the right ventricle is more muscular than normal, causing a characteristic boot-shaped (coeur-en-sabot) appearance as seen on anterior- posterior chest x-rays. "In this survey, the exposure of rats to smoking caused increase the level of hyper methylation in RASEF and occurrence of some changes including right ventricular hypertrophy, increasing the thickness right ventricular, and raising systolic blood pressure was observed." (PMID 37900914, 2023).
uveal melanoma (1 paper, 2021). A melanoma derived from melanocytes of the uveal tract. "A mutation in the Rab45/RASEF promoter region causes methylation and low RASEF expression in uveal melanoma, suggesting that Rab45/RASEF acts as a tumor suppressor gene." (PMID 34299309, 2021).
tumor (6 papers, 2015 to 2021). "Homozygous tumors with a methylated RASEF promoter region tend to display reduced survival compared with heterozygous tumors without methylation, suggesting loss of heterozygosity might be related to the aggressive behavior of the tumor." (PMID 32726977, 2020). "Rab45/RASEF was thought to act as a tumor suppressor, since it was initially discovered as a downregulated gene in human cutaneous malignant melanoma." (PMID 34299309, 2021). "RASEF (also known as Rab45) is an atypical GTPase, as a tumor suppressor gene in cutaneous malignant melanoma." (PMID 30845941, 2019). "Moreover, a clinical study showed that cancer patients with low Rab45/RASEF expression levels had significantly lower survival rates than patients with high Rab45/RASEF expression levels, suggesting that Rab45/RASEF may be a tumor suppressor gene." (PMID 34299309, 2021). "The function of Rab45/RASEF in cancer cells, either as a tumor suppressor or oncogene, is controversial." (PMID 34299309, 2021). "The Ras and EF-hand domain-containing (RASEF) gene, located on chromosome 9, region q21 is a candidate tumor suppressor gene." (PMID 32726977, 2020).
infection (3 papers, 2019 to 2024). The state of being infected such as from the introduction of a foreign agent such as serum, vaccine, antigenic substance or organism. "Infection with AAV1.RASEF was found to reverse cigarette smoke (CS)-induced downregulation of RASEF." (PMID 30845941, 2019). "AAV1.RASEF infection also obviously reduced the thickness of pulmonary arteriole walls." (PMID 30845941, 2019). "These include the tumor suppressor gene, RASEF (expressed only during the line 61 host response) and a gene involved in regulating cell-mediated immunity, HHLA2 (highly expressed in line 72 following infection)." (PMID 30678299, 2019).
cancer (2 papers, 2021 to 2022). A tumor composed of atypical neoplastic, often pleomorphic cells that invade other tissues. "RASEF overexpression promoted cell growth, whereas Rab45/RASEF knockdown reduced the growth of cancer cells." (PMID 34299309, 2021). "In contrast, Rab45/RASEF was reported to act as an oncogene in some cancer cells." (PMID 34299309, 2021).
RASEF also shares sentences with these, for which no sentence is quoted: colorectal cancer (1 paper); ischemic stroke (1); myeloid leukemia (1).